MGAT4B (alpha-1,3-mannosyl-glycoprotein 4-beta-N-acetylglucosaminyltransferase B)
Description:
Glycosyltransferase that catalyzes the transfer of GlcNAc from UDP-GlcNAc to the GlcNAcbeta1-2Manalpha1-3 arm of the core structure of N-linked glycans through a beta1-4 linkage and participates in the production of tri- and tetra-antennary N-linked sugar chains. Prefers complex-type N-glycans over hybrid-types. Has lower affinities for donors or acceptors than MGAT4A, suggesting that, under physiological conditions, it is not the main contributor in N-glycan biosynthesis.
Synonyms: GnT-IVb; GNT-IV
Tractability: Antibody: UniProt predicts a signal peptide or a membrane-spanning region. PROTAC: ubiquitination databases record sites on it; its protein half-life has been measured.
Gene: Protein-coding gene on chromosome 5 (179,797,597 to 179,806,979, reverse strand). Ensembl gene ENSG00000161013.
Subcellular location: Golgi apparatus membrane
Subcellular location (Human Protein Atlas): Nucleoplasm; Cytosol; Golgi apparatus; Vesicles
Pathways (Reactome):
Disease: Maturation of spike protein
Metabolism of proteins: N-Glycan antennae elongation
Gene Ontology:
Molecular function: alpha-1,3-mannosylglycoprotein 4-beta-N-acetylglucosaminyltransferase activity; protein binding; acetylglucosaminyltransferase activity; glycosyltransferase activity
Biological process: glycoprotein biosynthetic process; N-glycan processing; protein N-linked glycosylation; viral protein processing
Cellular component: endoplasmic reticulum; endoplasmic reticulum-Golgi intermediate compartment; Golgi membrane; Golgi stack
Genetic constraint (gnomAD): Loss-of-function variants: 38 observed, 72.62 expected, observed/expected ratio (o/e) 0.52, 90% interval 0.4 to 0.69. The upper end of that interval is the gene's LOEUF score, 0.69, which puts it in group 2 of 6, group 1 being the genes least tolerant of losing a copy. Missense variants: 686 observed, 742.11 expected, observed/expected ratio (o/e) 0.92, 90% interval 0.87 to 0.99. Synonymous variants: 373 observed, 313.78 expected, observed/expected ratio (o/e) 1.19, 90% interval 1.09 to 1.29.
Homologues: Orthologues: macaque MGAT4B (100% identical), chimpanzee MGAT4B (99% identical), mouse Mgat4b (99% identical), rat Mgat4b (99% identical), dog MGAT4B (98% identical), pig MGAT4B (98% identical), guinea pig MGAT4B (96% identical), rabbit MGAT4B (95% identical), tropical clawed frog mgat4b (86% identical), zebrafish mgat4b (80% identical), Drosophila melanogaster Mgat4a (41% identical), Drosophila melanogaster Mgat4b (26% identical). Paralogues in human: MGAT4A (60% identical), MGAT4C (26% identical), MGAT4D (25% identical).
Diseases named in the same sentence as MGAT4B in open-access papers:
MGAT4B is named in the same sentence as 16 diseases in open-access papers, as found by Europe PMC text mining. Sharing a sentence is not in itself a finding about the gene and the disease. The quoted sentences say what the papers report.
breast carcinoma (1 paper, 2022). "In breast cancer, MGAT1, MGAT2 and MGAT3 were downregulated, but MGAT4A, MGAT4B, and MGAT5 were increased." (PMID 36185271, 2022).
breast tumors (1 paper, 2022). "For example, events in CYB561 and CEACAM1 are enriched in HER2+, and E2F4, AP2A2, MGAT4B, and DUXAP9 events are enriched in basal-like breast tumors." (PMID 35044822, 2022).
glioma (1 paper, 2023). A benign or malignant brain and spinal cord tumor that arises from glial cells (astrocytes, oligodendrocytes, ependymal cells). "By silencing the MGAT4B gene in glioma cell lines U87 and U251, we proved that MGAT4B attenuated the proliferative capacity of glioma cell lines, by using the CCK8 assay." (PMID 36685667, 2023). "Therefore, we here deciphered the promoting role of MGAT4B in glioma growth, invasion, and macrophage recruitment." (PMID 36685667, 2023).
hepatocellular carcinoma (1 paper, 2014). A malignant tumor that arises from hepatocytes. "Number of Mgat4b transcripts increased considerably in diethylnitrosamine-induced hepatocellular carcinoma mice." (PMID 25243088, 2014).
Hyperglycemia (1 paper, 2023). An increased concentration of glucose in the blood. "The distinct effects of the two enzymes are also demonstrated in MGAT4A KO mice presenting with hyperglycemia due to selective N-glycan branching of the GLUT2 transporter by MGAT4A, despite the co-expression of MGAT4B in the pancreas." (PMID 37919266, 2023).
liver cancer (1 paper, 2025). An epithelial or non-epithelial malignant neoplasm that arises from the liver. "In liver cancer cells, studies have found that the expression of MGAT4B is upregulated and it is related to immune evasion." (PMID 40308606, 2025).
melanoma (1 paper, 2025). A malignant, usually aggressive tumor composed of atypical, neoplastic melanocytes. "Unlike prior studies that linked FUT8 mediated glycosylation to melanoma metastasis, our work demonstrates a causal role for MGAT4B in tumor initiation." (PMID 40424122, 2025). "Understanding the role of Mgat4b in melanoma may offer valuable insights into the mechanisms underlying tumor progression, metastasis, and perhaps even provide novel avenues for therapeutic intervention aimed at targeting the dysregulated glycosylation pathways characteristic of cancer cells." (PMID 40424122, 2025). "To dissect the molecular mechanisms by which Mgat4b regulates melanocyte functions, we knocked out Mgat4b in B16 mouse melanoma cells." (PMID 40424122, 2025). "Having demonstrated the pivotal role of mgat4b in early melanocyte development, we set out to assess its potential implications in melanoma tumor initiation." (PMID 40424122, 2025). "To investigate the involvement of Mgat4b in melanoma, we initially examined its expression in skin cutaneous melanoma (SKCM) using the cancer genome atlas (TCGA) database." (PMID 40424122, 2025). "We dissected and sectioned the control melanoma and the corresponding melanocyte aggregate from the mgat4b mutants." (PMID 40424122, 2025). "MGAT4B is overexpressed in human melanoma and is essential for melanoma initiation, as shown using the MAZERATI in vivo platform." (PMID 40424122, 2025). "Although melanocytes in the mgat4b mutant group showed signs of aggregation, they failed to initiate tumor formation demonstrating the indispensable role of mgat4b in initiating melanoma tumors in this zebrafish model." (PMID 40424122, 2025). "Our meta-analysis further reveals that melanoma patients with both the BRAFV600E mutation and elevated MGAT4B levels have significantly worse survival outcomes compared to those with only the BRAFV600E mutation." (PMID 40424122, 2025). "In melanoma, mgat4b disruption severely impairs tumor initiation, as transformed cells fail to adhere properly." (PMID 40424122, 2025). "Our study underscores the importance of selective N-glycan branching in both melanocyte development and melanoma initiation, suggesting MGAT4B as a promising therapeutic target for melanoma treatment." (PMID 40424122, 2025). "Molecular function enrichment analysis of melanoma, stratified by MGAT4B levels, revealed that among other pathways growth factor binding, cytoskeletal protein binding and integrin receptor binding were enriched." (PMID 40424122, 2025). "We first performed lectin blot analysis on both wildtype and Mgat4b knockout B16 mouse melanoma cells, where the available cell quantity allowed for effective enrichment and subsequent target identification." (PMID 40424122, 2025). "Remarkably, we observed elevated levels of MGAT4B in melanoma patients compared to normal individuals." (PMID 40424122, 2025). "Principal component analysis (PCA) of the sequencing data showed clear segregation between the three groups, confirming that the mgat4b mutant (M4b mut) cells are distinct from both untransformed wild-type melanocytes and control melanoma cells." (PMID 40424122, 2025). "Our investigation further revealed that melanoma patients with both the BRAFV600E mutation and elevated MGAT4B levels have significantly worse survival outcomes compared to those with only the BRAFV600E mutation (logrank test P value 0.0152)." (PMID 40424122, 2025). "Further exploration into the genetic alterations affecting MGAT4B revealed that ~10% of melanoma patients harbor amplifications in MGAT4B, which could explain aberrantly high levels of MGAT4B expression in affected individuals." (PMID 40424122, 2025). "Given Mgat4b’s involvement in orchestrating crucial developmental processes, including cell migration and patterning, there arises a compelling rationale to explore its function within the context of melanoma." (PMID 40424122, 2025).
melanoma (continued). "In future, this approach could yield novel therapeutic intervention selectively targeting MGAT4B for use in deterring melanoma growth." (PMID 40424122, 2025). "This specificity positions MGAT4B as a promising therapeutic target in melanoma." (PMID 40424122, 2025). "However, due to its broad toxicity, a drug selectively targeting MGAT4B could offer a more precise and effective melanoma therapy." (PMID 40424122, 2025). "In the wild-type group, we enriched for mature, nontransformed melanocytes, while the NTC and mgat4b mutant group included both transformed melanoma cells and melanocytes." (PMID 40424122, 2025). "To do this, we isolated mature melanophores from wild-type zebrafish and melanophores/melanoma cells from the skin of one month old MAZERATI zebrafish with and without mgat4b mutations." (PMID 40424122, 2025). "To test whether mitfa transcriptionally regulates mgat4b, we overexpressed MITF in B16F10 mouse melanoma cells and assessed its effects on MGAT4B levels." (PMID 40424122, 2025). "Remarkably, the control fishes expressing nontargeting sgRNA rapidly developed aggressive tumors within a month, whereas the mgat4b mutant animals failed to develop melanoma altogether." (PMID 40424122, 2025). "We utilized the well-established Mazerati model to genetically induce melanoma tumors in zebrafish, both with and without targeting mgat4b." (PMID 40424122, 2025). "In control melanoma cells, cell adhesion and migration processes were significantly enriched, but these were not similarly enriched in mgat4b mutant melanoma cells." (PMID 40424122, 2025).
prostate carcinoma (1 paper, 2024). A carcinoma that arises from epithelial cells of the prostate gland. "At the same time, MGAT4B, a gene responsible for glycosyltransferase synthesis, which is involved in aberrant glycosylation in cancer, appears to be associated to prostate cancer risk." (PMID 38612439, 2024).
cancer (5 papers, 2018 to 2025). A tumor composed of atypical neoplastic, often pleomorphic cells that invade other tissues. "Six genes (SLCO2A1, MGAT4B, SLC25A33, MCCC1, OIP5, and CTHRC1) have been shown to affect the tumorigenesis of other cancer types but not PC." (PMID 30024105, 2018).
MGAT4B also shares sentences with these, for which no sentence is quoted: tumor (5 papers); pancreatic cancer (3); Alzheimer disease (1); diabetes (1); endometrial cancer (1); skin cutaneous melanoma (1); Stroke (1).